CELF6 (CUGBP Elav-like family member 6)
Description:
RNA-binding protein implicated in the regulation of pre-mRNA alternative splicing. Mediates exon inclusion and/or exclusion in pre-mRNA that are subject to tissue-specific and developmentally regulated alternative splicing. Specifically activates exon 5 inclusion of TNNT2 in a muscle-specific splicing enhancer (MSE)-dependent manner. Promotes also exon exclusion of INSR pre-mRNA.
Synonyms: BRUNOL6
Tractability: PROTAC: its protein half-life has been measured.
Gene: Protein-coding gene on chromosome 15 (72,284,727 to 72,320,448, reverse strand). Ensembl gene ENSG00000140488.
Subcellular location: Nucleus; Cytoplasm
Gene Ontology:
Molecular function: RNA binding; nucleic acid binding
Biological process: regulation of alternative mRNA splicing, via spliceosome; mRNA splice site recognition
Cellular component: cytoplasm; nucleus; ribonucleoprotein complex
Genetic constraint (gnomAD): Loss-of-function variants: 31 observed, 38.65 expected, observed/expected ratio (o/e) 0.8, 90% interval 0.6 to 1.08. The synonymous counts are far from expectation, so gnomAD's model fits this gene poorly and the ratio says little. Missense variants: 536 observed, 550.79 expected, observed/expected ratio (o/e) 0.97, 90% interval 0.91 to 1.04. Synonymous variants: 291 observed, 239.4 expected, observed/expected ratio (o/e) 1.22, 90% interval 1.1 to 1.34.
Homologues: Orthologues: chimpanzee CELF6 (99% identical), macaque CELF6 (99% identical), pig CELF6 (98% identical), dog CELF6 (98% identical), rat Celf6 (96% identical), mouse Celf6 (95% identical), guinea pig CELF6 (79% identical), rabbit CELF6 (71% identical), zebrafish celf6 (65% identical), Caenorhabditis elegans unc-75 (51% identical), Drosophila melanogaster bru3 (47% identical). Paralogues in human: CELF4 (67% identical), CELF3 (67% identical), CELF5 (65% identical), CELF2 (46% identical), CELF1 (46% identical), RBM28 (23% identical).
Diseases named in the same sentence as CELF6 in open-access papers:
CELF6 is named in the same sentence as 16 diseases in open-access papers, as found by Europe PMC text mining. Sharing a sentence is not in itself a finding about the gene and the disease. The quoted sentences say what the papers report.
autism (5 papers, 2016 to 2019). Persistent deficits in social interaction and communication and interaction as well as a markedly restricted repertoire of activity and interest as well as repetitive patterns of behavior. "In particular, we found that Celf6, a gene that encodes an RNA-binding protein implicated in autism-related behavior and found to be widely expressed in neuromodulatory cell types throughout the mouse brain, is expressed in all Hcrt/Ox and MCH neurons." (PMID 28966976, 2017). "In the SFARI autism database, the following DE genes were registered: Celf6, which codes for a transcription associated protein and was common to CvN and CvI; Magel2 (melanoma antigen family L2), unique to CvI; and Ampd1 (adenosine monophosphate deaminase), also unique to CvI." (PMID 27782041, 2016). "By generating a genetic knockout of Celf6 in mice, the authors found several autism-related phenotypic behaviors including resistance to change and decreased ultrasonic vocalizations." (PMID 28769770, 2017). "Celf6 has been shown in other work to impact SERT function and to be associated with autism." (PMID 30073191, 2018). "Overall a very interesting and potentially valuable manuscript examining in mice (wild-type and Celf6 mutant genotypes) the effects of 16 mg/kg/day fluoxetine exposure vs. vehicle during gestation with different stopping points for treatments on offspring behaviors relevant to autism." (PMID 30073191, 2018).
cervical cancer (2 papers, 2021 to 2022). A primary or metastatic malignant neoplasm involving the cervix. "Recent research demonstrated that the minor allele “C” of a single-nucleotide polymorphism in CELF6 is associated with increased risk of cervical cancer." (PMID 35910766, 2022). "A single nucleotide variation, rs4777498, in CELF6, regulated by miR-375, was previously found to be associated with cervical cancer susceptibility." (PMID 34681716, 2021). "The first observations on the association of CELF6 with cancer came in a study on susceptibility to cervical cancer, in which the minor allele “C” of rs4777498 in the CELF6 gene accounted for an increased risk of this malignancy." (PMID 34681716, 2021).
colon cancer (2 papers, 2019 to 2022). "Previous research reports stated that CELF6 is generally down-regulated in colon cancer and breast cancer, and acts as a tumor suppressor." (PMID 35910766, 2022). "Both CELF6 mRNA and protein expression levels were significantly lower in colon cancer tissues than those in nontumor colon tissues." (PMID 31534127, 2019).
colorectal cancer (2 papers, 2019 to 2023). A primary or metastatic malignant neoplasm that affects the colon or rectum. "To determine the function of CELF6 in cancer, we analyzed TCGA RNA-seq data set in colorectal cancer and performed immunohistochemistry assay in normal and cancerous colon tissues." (PMID 31534127, 2019).
myotonic dystrophy (2 papers, 2019 to 2022). An inherited progressive disorder affecting the muscles. "CELF6 is associated with the pathogenesis of myotonic dystrophy by regulating muscle-specific alternative splicing (DM)." (PMID 36066672, 2022). "CELF6, a member of the CELF family of RNA-binding proteins, regulates muscle-specific alternative splicing and contributes to the pathogenesis of myotonic dystrophy (DM), however the role of CELF6 in cancer cell proliferation is less appreciated." (PMID 31534127, 2019).
breast carcinoma (1 paper, 2022). "In triple-negative breast cancer, CELF6 up-regulates the expression of FBP1 by stabilizing the mRNA expression of FBP1 and suppresses the development of breast cancer." (PMID 35910766, 2022).
esophageal carcinoma (1 paper, 2024). A primary or metastatic malignant neoplasm involving the esophagus. "However, and according to our data, there are no studies describing the methylation of these genes in other tumors, with the exception of one publication describing the hypermethylation of CELF6 in oral squamous cell carcinoma and that of MTHFD2 in esophageal carcinoma." (PMID 39305372, 2024).
hepatocellular carcinoma (1 paper, 2019). A malignant tumor that arises from hepatocytes. "We also knocked out CELF6 expression in human hepatocellular carcinoma cell line HepG2, both qPCR and immunoblotting demonstrated that p21 expression was dramatically reduced in CELF6 knock out HepG2 cells." (PMID 31534127, 2019).
lung adenocarcinoma (1 paper, 2022). A carcinoma that arises from the lung and is characterized by the presence of malignant glandular epithelial cells. "Two lung cancer types (LUAD, lung adenocarcinoma; LUSC, lung squamous cell carcinoma) have lower CELF6 expression levels, too." (PMID 35910766, 2022).
lung carcinoma (1 paper, 2022). "In summary, we made an extensive analysis of the transcriptome profile of gene expression and alternative splicing by CELF6-OE, providing a global understanding of the target genes and underlying regulation mechanisms mediated by CELF6 in the pathogenesis and development of lung cancer." (PMID 35910766, 2022). "However, the underlying mechanism of lower expressed CELF6 in lung cancer tissues is still unclear." (PMID 35910766, 2022). "To investigate CELF6 expression pattern and its influence on prognosis in lung cancer, we used GEPIA2 and KM-plotter to analyze gene expression level and survival time using public datasets." (PMID 35910766, 2022). "Based on the identified functions of CELF6, we predict that it could also influence the phenotypes of lung cancer cells by acting as a tumor suppressor." (PMID 35910766, 2022). "In this study, we increased CELF6 manually in lung cancer cell line (A549) and utilized transcriptome sequencing (RNA-seq) technology to screen out differentially expressed genes (DEGs) and alternative splicing events (ASEs) after CELF6 over-expression (CELF6-OE)." (PMID 35910766, 2022). "Therefore, it is likely that CELF6, as an RBP, has important regulatory functions in lung cancer, which has not been previously investigated." (PMID 35910766, 2022).
non-small cell lung carcinoma (1 paper, 2022). A group of at least three distinct histological types of lung cancer, including non-small cell squamous cell carcinoma, adenocarcinoma, and large cell carcinoma. "To study its potential mechanism in non-small cell lung cancer, we used the A549 cell line as a model to analyze the consequences of CELF6 over-expression." (PMID 35910766, 2022). "Further research on CELF6-regulated alternative splicing would be helpful to accurately understand the signaling network that guides the occurrence of non-small cell lung cancer, as well as the potential of CELF6-targeting therapies." (PMID 35910766, 2022).
cancer (3 papers, 2019 to 2022). A tumor composed of atypical neoplastic, often pleomorphic cells that invade other tissues. "CELF6 had significantly higher expression levels in normal tissue compared with in tumor tissue in 16 out of the 31 cancer types, whereas significantly higher expression levels of CELF6 in tumor tissue were only observed in LAML and PCPG." (PMID 35910766, 2022). "CELF6-OE was observed to negatively regulate the expression of many genes related to cancer inflammation." (PMID 35910766, 2022). "We found that in A549 cells, CELF6 may regulate tumorigenesis and cancer progression by repressing the expression of immune response genes." (PMID 35910766, 2022). "Using GEPIA2 software, 16 of the 33 cancer types from TCGA show the down-regulation of CELF6, indicating that CELF6 may play an important role in the pathogenesis and progression of various tumors." (PMID 35910766, 2022). "Thus, we propose that CELF6 is a potential tumor suppressor, CELF6 regulates cancer cell proliferation and cell cycle progression via modulating p21 stability." (PMID 31534127, 2019). "In this report, we aimed to study the function of CELF6 in cancer cell proliferation." (PMID 31534127, 2019).
tumor (3 papers, 2019 to 2024). "In conclusion, we successfully applied RNA-seq technology to prove that CELF6 regulates alternative splicing, and that the functions of splicing factors are associated with tumor immunity." (PMID 35910766, 2022). "In this study, GEPIA2 and KM-plotter software were used to analyze TCGA data and the results indicated that CELF6 showed lower expression levels in most tumor types compared with in matched normal tissue." (PMID 35910766, 2022). "Over-expression of CELF6 inhibits tumor cell proliferation, colony formation, cell migration and invasion by directly binding to the 3′UTR of FBP1 and stabilizing FBP1 transcripts." (PMID 35910766, 2022). "A recent study reported that CELF6 may be a potential tumor suppressor, and may regulate cell proliferation and cell cycle progression by affecting the stability of p21." (PMID 35910766, 2022). "Collectively, these data demonstrate that CELF6 might be a potential tumor suppressor, CELF6 regulates cell proliferation and cell cycle progression via modulating p21 stability." (PMID 31534127, 2019). "In this study, it is speculated that CELF6 may function as a tumor suppressor in NSCLC." (PMID 35910766, 2022).
CELF6 also shares sentences with these, for which no sentence is quoted: autism spectrum disorder (2 papers); lung squamous cell carcinoma (1); oral squamous cell carcinoma (1).